INS (insulin)
Diseases named in the same sentence as INS in open-access papers (continued):
Sharing a sentence is not in itself a finding about the gene and the disease.
Insulin resistance (continued). "We had earlier shown that LP-programmed T2D rats had compromised insulin signaling leading to peripheral insulin resistance." (PMID 35334815, 2022). "Maternal insulin resistance (elevated TGs, insulin, and weight gain) led to activation of de novo lipogenic and pro-inflammatory pathways in liver from offspring at 1 year of age." (PMID 36935840, 2022). "Insulin resistance is a pathological condition in which the physiological response to insulin stimulation of target tissues such as the liver, the skeletal muscle, and the adipose tissue, is impaired." (PMID 36432614, 2022). "Obesity is closely correlated with insulin resistance, and increased adipocyte size indicates reduced insulin sensitivity." (PMID 35409375, 2022). "In a study that evaluated insulin resistance by the insulin sensitivity index suggested that participants with CKD and obesity had a lower insulin sensitivity index." (PMID 35054932, 2022). "Among the variables, the HOMA2-IR and HOMA2-B are indexes of insulin resistance and insulin secretory function respectively." (PMID 34996484, 2022). "A rise in HOMA-IR and a decline in ISI were found in the DM group, revealing the imbalance between insulin resistance and insulin sensitivity." (PMID 36613249, 2022). "This study constructed a well-developed rabbit model of T2DM, featuring elevated serum glucose, triglyceride, cholesterol, and insulin concentrations and a higher insulin resistance level compared with control rabbits." (PMID 36741851, 2022). "In diabetic patients, a compensatory increase in the level of insulin secondary to insulin resistance has been suggested as the possible mechanism of cancer." (PMID 35223684, 2022). "Some novel cues linking insulin signaling, insulin resistance, atherogenic dyslipidemia and adipose tissue dysfunction will be provided in the following part of this article." (PMID 35055114, 2022). "Chronic hyperglycemia leads to a decrease in glucose-stimulated insulin secretion and an increase in insulin resistance." (PMID 35844351, 2022). "When compensatory insulin secretion from pancreatic β-cells is insufficient to maintain circulating glucose concentrations in response to insulin resistance, GDM occurs in pregnant women." (PMID 35449053, 2022). "The formula used to calculate the homeostatic model assessment of insulin resistance (HOMA-IR) is: fasting plasma glucose (mmol/l) times fasting serum insulin (μIU/mL) divided by 22.5." (PMID 35287731, 2022). "Several cellular mechanisms are involved in obesity pathologies such as the metabolic pathways activated by directly influencing the insulin signaling in insulin-target tissues such as the liver, eventually leading to insulin resistance." (PMID 36778595, 2022). "Skeletal muscle insulin resistance plays a critical role in the onset of T2DM due to the decreasing in the insulin-stimulated glucose uptake." (PMID 36368953, 2022). "The present investigation showed that infusion of MSCs substantially suppressed damage of β cells and enhanced their repair as indicated by the improvement of glucose, insulin, C-peptide, insulin resistance, and β cell function." (PMID 35463813, 2022). "GPR39 augments insulin secretion under conditions of increased demand; e.g., age-dependent and diet-induced insulin resistance." (PMID 35875352, 2022). "In fact, CB chemosensitivity in prediabetic patients was shown to be correlated with insulin levels and with insulin resistance." (PMID 35600301, 2022). "Since obesity is associated with the development of insulin resistance, we next determined the effect of HFD on glucose and insulin tolerance in WT and GSDMD KO mice." (PMID 36065376, 2022).
Insulin resistance (continued). "Although post-translational modification of IRS-1 is crucial for the regulation of insulin sensitivity, a number of studies have found that low IRS-1 protein levels are closely associated with the development of insulin resistance and T2DM." (PMID 35328400, 2022). "SIRT1 activation reduce insulin resistance, enhances insulin sensitivity via PGC1-α (PPARγ co-activator 1α), implementing beneficial effects in obesity and diabetes type 2." (PMID 35163422, 2022). "During the last decade, it has been reported that various miRNAs induced by SFA participate in the development of hepatic insulin resistance by targeting the translation of proximal insulin signaling molecules at the post-transcriptional level." (PMID 35328400, 2022). "But if rising insulin resistance is a consequence of excess adiposity, nutrient overload, and caloric imbalance, we would expect there to be a difference in fasting insulin and insulin resistance, but little difference in glucose variability." (PMID 36570168, 2022). "Clinical investigators noted also that most people with insulin resistance and a high plasma insulin concentration had hypertension as a part of a cluster of metabolic conditions that included being overweight, increased fasting glucose, and dyslipidemia." (PMID 36289636, 2022). "In our study, hormones like testosterone, sex hormone binding globulin, fasting insulin, and homeostatic model assessment of insulin resistance were significantly higher in the PCOS group compared with non-PCOS group." (PMID 35642189, 2022). "Insulin resistance (IR) is described as a defective physiological response to insulin stimulation of targeted cells, primarily these in the liver, muscles, and various types of adipose tissue." (PMID 35454311, 2022). "As expected, the intraperitoneal insulin tolerance test (IPITT) revealed significant peripheral insulin resistance in the skmPAK1-iKO mice, with area over the curve (AOC) decreased by ~35%; Dox was confirmed to be without effect on IPITT." (PMID 35222279, 2022). "Later phase of pregnancy is associated with increase in insulin resistance, necessary for maintaining increased levels of nutrients for fetal transfer, and these data suggest that obesity-related decrease in the levels of TG-myristic acid may alter the physiological insulin homeostasis in pregnancy." (PMID 35871677, 2022). "This leads to impaired insulin secretion, insulin resistance, and hyperlipidemia, which promote MetS development." (PMID 36558417, 2022). "Although there is a clear relationship between Ang II and its role in developing insulin resistance in the cardiovascular, hepatic, and muscular systems, the effect of Ang II on insulin signaling in adipose cells, it is still under discussion." (PMID 35682723, 2022). "Hyperglycemia, generated as a result of insulin resistance, stimulates β-cells to secrete more insulin." (PMID 36077491, 2022). "The major pathophysiology of type 2 diabetes mellitus (T2DM) is increased insulin resistance and decreased insulin secretion." (PMID 35672759, 2022). "In type 2 diabetes, there is persistent hyperglycemia as β cells are unable to produce insulin, or there is a development of insulin resistance by various tissues." (PMID 35458669, 2022). "Mean glucose, glucose post-OGTT, fasting insulin, insulin resistance, and triglycerides were greater in patients; mean total-cholesterol and HDL-cholesterol were reduced in patients." (PMID 37449481, 2022). "Insulin resistance is defined as a dysfunction in the ability of target tissues to mount a normal response to insulin." (PMID 36589543, 2022). "We acquired the T2DM rat model for further investigation to determine the efficacy of hUC-MSCs-sEVs on improving insulin resistance and insulin sensitivity in diabetic rats." (PMID 35336023, 2022). "Sixth, this study used HOMA-IR, which is calculated by using fasting insulin and glucose levels, as an index for insulin resistance." (PMID 36086748, 2022).
Insulin resistance (continued). "These mice also presented insulin resistance (P<0.01), glucose intolerance (P<0.001), impaired glucose-stimulated insulin secretion (GSIS) and were less responsive to the physiological net ROS production induced by glucose stimulus." (PMID 35669687, 2022). "IRS-1 genetic variations have a deleterious effect on insulin resistance, reduced ability to store subcutaneous fat, and disrupted insulin signalling in liver and muscle, resulting in ectopic deposition of lipids." (PMID 36035124, 2022). "This advanced phenotype is prevented by rescuing CEACAM1 in the liver, providing further in vivo demonstration of the critical role that CEACAM1-dependent insulin clearance pathways play in the pathogenesis of hepatic insulin resistance and NAFLD/NASH." (PMID 36009446, 2022). "The hyperglycemia would further stimulate insulin secretion, creating a vicious cycle, leading to insulin resistance and the development of T2DM." (PMID 36326689, 2022). "Metformin has been proven to be effective on insulin resistance parameters, such as fasting insulin levels, dyslipidemia, Body Mass Index (BMI), oxidative stress, and inflammatory markers." (PMID 36009471, 2022). "Several lines of evidence indicate that the impairment of proximal insulin signaling results in insulin resistance in obesity and T2D." (PMID 35074429, 2022). "For instance, NF-kB-activation in the lung attenuates the suppression of hepatic glucose production by insulin and induces insulin resistance in peripheral tissues." (PMID 36013497, 2022). "Insulin resistance (IR) is a disorder of glucose homeostasis, involving reduced insulin sensitivity (IS) in muscle, adipose tissue, liver, and other tissues where insulin action is involved." (PMID 36361210, 2022). "The product of blood glucose and serum insulin levels (HOMA-IR equivalent) indicates insulin resistance, and this index was elevated in WT given HFHSD; however, it was lower in SOD1−/− given HFHSD." (PMID 35883894, 2022). "The present study revealed that combined supplementation with GTC and CCA significantly decreased insulin resistance index (AUCins×glu) values and improved insulin sensitivity index (Matsuda index) values after the high-fat and high-carbohydrate meal." (PMID 36501092, 2022). "Leptin treatment prevented liver fat deposition and insulin resistance, induced greater insulin and leptin signaling capacity, decreased gene expression of orexigenic signals at the hypothalamic level, and induced browning in retroperitoneal adipose tissue." (PMID 35684076, 2022). "The existence of such selective insulin resistance leads to a recent proposal of tissue- and/or pathway-specific insulin action." (PMID 39872684, 2022). "Insulin synthesis is thought to be enhanced in pancreatic β-cells in the early stages of T2DM to compensate for insulin resistance." (PMID 36613674, 2022). "Insulin resistance is a condition in which the potency of insulin on target cells, particularly adipocytes, hepatocytes, and skeletal muscles, is breached, resulting in hyperglycemia by interfering with glucose utilization and enhancing hepatic glucose output." (PMID 36557843, 2022). "In our animal model of dietary-induced obesity and insulin resistance, SG increased whole-body insulin-mediated glucose disposal, as shown by the glucose-AUC to insulin-AUC ratio compared with sham-operated rats." (PMID 35131692, 2022). "Participants with T2DM treated with INI had faster walking speed, increased cerebral blood flow on fMRI and lower plasma insulin and insulin resistance as compared T2DM on placebo." (PMID 35903156, 2022). "It exerts its main action on the insulin-signaling pathway by increasing P13-K activity and thus reducing insulin resistance." (PMID 35924049, 2022). "While T1DM results from autoimmune destruction of pancreatic β cells, T2DM is found in patients with insulin resistance, which initially results in β-cell overdrive and increased insulin secretion, which eventually drives β-cell exhaustion." (PMID 35203680, 2022).
Insulin resistance (continued). "Adipose tissue macrophage modulates insulin action through different mechanisms, with M1 macrophage promoting insulin resistance while M2 macrophage enhancing insulin sensitivity." (PMID 36119080, 2022). "The largest subgroup (MOD, 45% of participants) is characterised by mild obesity, insulin resistance and preserved insulin secretion." (PMID 35763031, 2022). "Excess of abdominal fat and insulin resistance (IR) are key factors for MetS, and both conditions are related to chronic inflammation in insulin-responsive tissues." (PMID 36676927, 2022). "Type 2 diabetes mellitus (T2DM) is a metabolic disorder, in which insulin-mediated glucose uptake in peripheral tissues, primarily the liver, muscle, and adipose tissues, decreases due to insulin resistance (IR)." (PMID 36295064, 2022). "During type II diabetes progression, an increase in HbA1c content associated with long-term hyperglycemia is generally observed as part of insulin resistance, along with an increase in the insulin content in the blood." (PMID 35208513, 2022). "We used the homeostasis model assessment (HOMA) to calculate the insulin resistance index HOMA-IR, which reveals the insulin resistance based on serum insulin levels (IU/mL) and serum glucose levels (mmol/L)." (PMID 36213511, 2022). "Insulin resistance is the decreased ability of a given dose of insulin to increase glucose uptake from an individual’s circulation compared to the normal nondiabetic population." (PMID 35883827, 2022). "PPARδ activation reduces insulin resistance by regulating mitochondrial oxidation capacity in skeletal muscle, and the glucose-insulin cycle, thus enhancing glucose utilization and reducing triacylglycerol deposition." (PMID 35957821, 2022). "Adiponectin, the most crucial insulin-sensitizing, anti-inflammatory adipokine, and resistin, a newly discovered adipokine directly related to insulin resistance, are the main adipokines influenced by obesity." (PMID 36355818, 2022). "Taken together, these data indicate that the insulin-stimulated rates of ATP synthesis are negatively affected very early in the pathogenesis of insulin resistance and in T2D." (PMID 36876056, 2022). "Future studies conducted on the role of miRNAs on selective hepatic insulin resistance warrant the understanding of this paradoxical action of insulin." (PMID 36479211, 2022). "Chronic hypersecretion of insulin promotes both insulin resistance and hypersecretion of leptin from the adipose tissue." (PMID 36381191, 2022). "We found that AIP cases with periodontitis had increased insulin and C-peptide, which is consistent with insulin resistance." (PMID 36013449, 2022). "Increased insulin resistance or decreased insulin sensitivity in T1D is primarily ascertained by measures of increased body weight together with the amount of insulin needed to achieve and maintain the recommended target glucose levels." (PMID 35745754, 2022). "This compensatory insulin hypersecretion promotes abdominal obesity, increasing insulin resistance through adipocytokines release and subsequent insulin hypersecretion, leading to more obesity and to each MetS component." (PMID 36233611, 2022). "Reducing BCAAs intake can improve postprandial insulin sensitivity, so BCAAs intake is considered an indicator of insulin resistance and a predictor of diabetes development." (PMID 36530444, 2022). "Insulin resistance (IR) refers to the physiological concentration of insulin required to promote the ability of peripheral tissue cells to use glucose, and 50-80% of PCOS patients have varying degrees of IR." (PMID 36386912, 2022). "Conversely, serum adiponectin levels correlated negatively with insulin, HOMA-IR, and WHR—parameters more related to insulin resistance/insulin sensitivity than BMI or weight." (PMID 35276837, 2022).
Insulin resistance (continued). "Insulin resistance (IR) refers to an impairment in insulin-mediated control of glucose homeostasis, which is characterized by hyperinsulinemia and defective response of target cells or a whole organism to the insulin exposure." (PMID 35784578, 2022). "SkmPAK1-iKO mice exhibit peripheral insulin resistance, defects in hindlimb skeletal muscle insulin-stimulated GLUT4 translocation, and show whole body glucose intolerance." (PMID 35222279, 2022). "The results of the clinical trial showed that sitagliptin exerted pharmacological effects such as promoting insulin secretion, inhibiting islet β cell apoptosis, improving insulin resistance, anti-inflammatory, anti-oxidative stress, and anti-fibrosis." (PMID 36699034, 2022). "During illness, the observed insulin resistance is mainly due to the inability of insulin to inhibit liver gluconeogenesis." (PMID 36992767, 2022). "A recent study revealed that Tau deletion in mice results in insulin resistance, which led us to explore the effects of increased Tau or phosphorylated Tau on insulin signaling." (PMID 36589543, 2022). "Previous studies have revealed that dysregulation of hepatic insulin signaling results in impaired glucose homeostasis and the development of insulin-resistance during aging." (PMID 35871686, 2022). "Pro-inflammatory cytokines such as tumor necrosis-alpha (TNF-α), interleukin-1 (IL-1), and interleukin-6 (IL-6), which are increased in response to obesity, induce insulin resistance at a molecular level by modulating the insulin signaling pathway." (PMID 35883605, 2022). "For example, Groh and colleagues demonstrated that mice with sarcoglycan complex deficiency in adipose tissue and skeletal muscle had glucose-intolerance and insulin resistance specifically due to impaired insulin-stimulated glucose uptake in skeletal muscles." (PMID 35769078, 2022). "Leptin can antagonize insulin and produce insulin resistance, while adiponectin can improve insulin sensitivity by increasing fatty acid oxidation and glucose uptake in skeletal muscle cells." (PMID 35056765, 2022). "Impairment of hepatic insulin sensitivity and induction of insulin resistance are among molecular mechanisms through which TCF7L2 rs7903146 variant increases the risk of type 2 diabetes and its most common comorbidity." (PMID 35585604, 2022). "Here, we demonstrate that BATF3-deficiency leads to the development of metabolic syndrome as characterized by insulin resistance, blood glucose and serum insulin levels, increased body weight and white adipocyte size, and development of hepatosteatosis." (PMID 35812447, 2022). "Impaired response to exogenous insulin characterizes insulin resistance in type 2 diabetes mellitus." (PMID 36013252, 2022). "Second, in silico experiments investigating the association between MGF and insulin signaling and the PI3K-AKT signaling pathways revealed the possibility of improving insulin resistance through a decrease in fat accumulation." (PMID 36499655, 2022). "It is possible that reduced GSIS and high insulin sensitivity at a young age protect the Ghsr−/− mice from developing insulin resistance and T2D in aging." (PMID 35327599, 2022). "METS-IR (Metabolic Score for Insulin Resistance), an established index of insulin sensitivity, was also derived." (PMID 35966525, 2022). "Consecutively, hyperglycemia can induce excessive peroxide production, which eventually leads to impaired insulin secretion and insulin resistance by promoting multiple oxidative stress pathways.There is growing evidence about dyslipidemia is a cause of IR." (PMID 36992743, 2022). "Chronic exposure to these EVs however, induced insulin resistance, as we observed adipocytes‐treated with ZF derived ‐EVs displayed reduced insulin‐stimulated 2‐deoxyglucose uptake compared to cells exposed to control EVs." (PMID 38938664, 2022). "PPARG has the potential to improve insulin resistance since its activation increases peripheral tissue sensitivity to insulin." (PMID 36289871, 2022).